AHR (aryl hydrocarbon receptor)
Diseases named in the same sentence as AHR in open-access papers (continued):
Sharing a sentence is not in itself a finding about the gene and the disease.
colitis (continued). "In addition, alpinetin (15, 30 mg/kg) obviously increased the mRNA and protein expressions of AhR target gene CYP1A1 in colons of colitis mice." (PMID 30166541, 2018). "In mice with DSS-induced colitis, knockout of AhR obviously increases the disease severity." (PMID 30166541, 2018). "Also Lactobacillus bulgaricus OLL1181 was found to activate the AHR pathway and inhibit colitis in a mouse model." (PMID 30120222, 2018). "To assess whether these perturbed responses to DSS colitis were cell type specific, we generated T cell specific AhR KO mice (LckAhR−/−) and exposed them to the 2% DSS challenge." (PMID 27068235, 2016). "DSS-induced colitis was ameliorated by pretreatment with the potent AhR activator, TCDD, in mice." (PMID 24905409, 2014). "Activation of the AhR ameliorates the inflammation and disease activity of colitis mice." (PMID 24416230, 2014). "Interestingly, a recent study in dextran sulfate sodium-induced colitis mice reported that the attenuation of AhR expression resulted in a protective effect." (PMID 24236236, 2013). "In this study, we examined the effect of AhR activation on DSS-induced colitis in the mouse model." (PMID 21858153, 2011). "In this context, the current study demonstrates, using TCDD, how AhR activation leads to selective upregulation of FoxP3+ Tregs and down regulation of Th17 cells through epigenetic regulation, leading to amelioration of an inflammatory disease such as colitis." (PMID 21858153, 2011). "Additionally, astrocyte activity and CNS inflammation are modulated by type I interferons and tryptophan metabolites via the aryl hydrocarbon receptor, and administration of an aryl hydrocarbon receptor agonist can attenuate intestinal inflammation in mouse models of colitis." (PMID 39256304, 2025). "In addition, studies in mice lacking the IBD susceptibility gene Card9 have shown that a lack of microbiota capable of producing AhR agonists is associated with an increased risk of colitis." (PMID 40825672, 2025). "The Kyn-AhR axis additionally polarizes macrophages toward M2 phenotypes and expands Treg populations, while AhR blockade in AOM/DSS models reverses TAM polarization, suppresses Tregs, and enhances CD8+ T cell infiltration to ameliorate colitis-associated carcinogenesis." (PMID 41488637, 2025). "However, our analysis demonstrates that AhR‐dependent induction of BD1 in CECs may be the key potential mechanism by which AhR can circumvent microbial dysbiosis and colitis." (PMID 40410944, 2025). "Our studies suggest that AhR may function as a post-transcriptional regulator of α-defensin 1 in normal individuals and that in CD patients, dysregulation in AhR and α-defensin 1 may initiate the inflammatory colitis process." (PMID 39894796, 2025). "While it has been demonstrated that activation of AhR inhibits colitis through many signaling pathways that involve immune cells, we discovered a new potential mechanism by which AhR can prevent colonic inflammation and colitis through AhR-mediated transcriptional induction of α-defensin 1 in IECs." (PMID 39894796, 2025). "The consequences of AhR activation hence appear to be ligand-specific, as while some AhR ligands that possess short half-lives and bind to AhR only transiently have been reported to be protective against colitis, other ligands have been reported to induce a proinflammatory response." (PMID 38448800, 2024). "The remission of colitis in NMSIAA group could be related to IAA activation of AHR and ERK pathway." (PMID 39458442, 2024). "Importantly, AhR activation in IECs is also involved in barrier repair during colitis." (PMID 39767818, 2024). "Furthermore, it has been shown that the activation of AHR by various endogenous ligands inhibits the NF-κB signaling pathway, reducing the expression of IL-1β and IL-6 in conditions such as periodontitis, bronchitis, and colitis." (PMID 39465158, 2024).
colitis (continued). "Some limitations in the current report can be addressed in future studies by including an expansion of the control mice population and further investigating the established sex differences that could play a role in AhR activation by I3C during colitis conditions." (PMID 38397081, 2024). "However, endogenous ligands including HSC70 may also play a role in AhR activation as a previous study showed a regulatory role of HSC70-AhR signaling in a colitis model." (PMID 39215111, 2024). "Furthermore, I3C and ITE (both AHR agonists) were shown to attenuate colitis by upregulating Treg." (PMID 38998940, 2024). "In line with this, AHR-deficient mice exhibit a marked reduction in the number of ILC22 and the secretion of IL-22 and are unable to mount a protective response during Citrobacter Rodentium infection, a mouse model that mimics human colitis induced by attaching and effacing enterotoxigenic E. coli." (PMID 38674118, 2024). "Thus, the objective of our study was to use mice with IEC-specific AhR deletion to understand how the provision of DIM in the diet would affect TLT formation during a model of DSS-induced colitis through AhR-mediated signaling processes at the intestinal epithelium." (PMID 39337636, 2024). "Furthermore, endogenous ligands for AhR may block the NF-κB signaling pathway and lessen local inflammation in bronchitis, periodontitis and colitis." (PMID 36721094, 2023). "In addition, Qing Dai and indigo may improve colitis by activating AHR to upregulate IL-10 and IL-22." (PMID 37179416, 2023). "Thus, AHR has the potential as a drug target for the treatment of colitis." (PMID 37179416, 2023). "A study assessing TCDD-mediated AhR signaling and its influence on the course of Crohn`s disease demonstrated faster recovery of TCDD-fed mice from 2,4,6-trinitrobenzenesulfonic acid (TNBS)-induced colitis, which was associated with increased numbers of Foxp3+ Tregs in the intestines." (PMID 36875083, 2023). "In addition to toxic effects, TCDD was proven to have a positive impact on organisms by activating AHR, such as relieving colitis symptoms, decreasing the viral load and the levels of proinflammatory cytokines, and suppressing experimental autoimmune encephalitis." (PMID 37179416, 2023). "Since the loss of PARP7 expression increases AHR signaling, we hypothesized that Parp7−/− mice would be less sensitive to the negative impacts associated with colitis and intestinal inflammation." (PMID 35055106, 2022). "Besides, research on mice lacking the IBD susceptibility gene Card9 showed that the absence of an altered microbiome capable of generating AhR agonists was linked to an increased risk of colitis." (PMID 35784338, 2022). "The aryl hydrocarbon receptor (AHR) is an environmental sensor that integrates microbial and dietary cues to influence physiological processes within the intestinal microenvironment, protecting against colitis and colitis-associated colorectal cancer development." (PMID 35383166, 2022). "We hypothesized that AhR activation induces the tolDCs by downregulating costimulatory molecules such as CD80, CD83, CD86, and inflammatory cytokines that may prevent the pathogenic processes underlying colitis in mice." (PMID 35461286, 2022). "Moreover, a previous study showed that oral administration of the AhR agonist β-naphthoflavone decreased DSS-induced colitis severity and the production of pro-inflammatory cytokines, such as tumor necrosis factor (TNF)-α, IL-6, and IL-1β, which was consistent with our results." (PMID 36613665, 2022). "Other studies also suggest that Trp plays a role in the recovery of colitis and in the function of intestinal homeostasis by caspase recruitment domain family member 9 (Card9), calcium-sensing receptor (CaSR), and aryl hydrocarbon receptor (AHR) ligands in the intestine." (PMID 35747264, 2022).
colitis (continued). "Furthermore, the AhR has been shown to be an important regulator of T cell immunity in intestinal inflammation, regulating IL-17, Foxp3, IL-10, and IL-22 expression, and altogether ameliorating colitis symptoms and maintaining intestinal homeostasis." (PMID 32366032, 2020). "The lack of functional AHR signaling in such animals may explain why they are more susceptible to colitis induced experimentally, e.g., by trinitrobenzene sulfonic acid (TNBS) or dextran sulfate sodium (DSS)." (PMID 32784381, 2020). "Therefore, we investigated the anticolitis efficacy of baicalein and explored the potential mechanisms that activating AhR could promote Treg cell differentiation and recover Th17/Treg balance in colitis mice." (PMID 33082710, 2020). "Moreover, these AHR-expressing Treg cells inhibit T cell-induced wasting disease and colitis." (PMID 31683543, 2019). "Moreover, dietary Trp alleviates SDS-induced colitis by AHR in mice." (PMID 29682569, 2018). "Also, oral administration of the AhR agonist β-naphthoflavone attenuated DSS-evoked colitis." (PMID 26264025, 2015). "This in vivo study also found that both neutralizing the IL-22 via injections of a blocking antibody of IL-22 and treatment with the AhR antagonist, 2-metal-2h-pyrazole-3-carboxylic acid, contributed to suppression of the production of cytokine IL-22 and acceleration of the symptoms of colitis." (PMID 24905409, 2014). "In addition to the direct effect on the differentiation of Tregs and Th17 cells, AhR activation may increase prostaglandin E2 production in the colon, which may lead to amelioration of colitis." (PMID 21858153, 2011). "In summary, our studies suggest that during colitis, activation of AhR by TCDD may promote anti-inflammatory activity primarily through epigenetic regulation of Foxp3 and IL-17 gene promoters leading to preferential differentiation of Tregs and inhibition of Th17 cells." (PMID 21858153, 2011). "The preceding works demonstrate that HQD reshapes the gut microbiota to amplify tryptophan metabolism and that AhR antagonism abolishes HQD-induced ISC differentiation and colitis resolution." (PMID 41530817, 2026). "Collectively, these data demonstrate that microbiota depletion prevents HQD from activating the AhR pathway, thereby abrogating its ability to promote ISC differentiation and mucosal repair in DSS colitis." (PMID 41530817, 2026). "The tryptophan-AhR axis drives Intestinal stem cell (ISC) proliferation, promotes mucosal repair, and suppresses inflammation in experimental colitis, representing a promising therapeutic target." (PMID 41530817, 2026). "We assessed AhR activation by measuring the mRNA expression of its target gene, CYP1A1, which was notably reduced in mice with colitis." (PMID 40410944, 2025). "Similar to I3C, our data showed that TCDD upregulated AhR, CYP1A1 and mBD‐1 in CECs from control and colitis (anti‐CD40/ DSS‐ induced) animals." (PMID 40410944, 2025). "The study discovered that the intervention of L. paracaseiL21 resulted in a significant increase in the content of SCFAs and the levels of AhR and HIF1α in the colon of mice with DSS-induced colitis, leading to an upregulation of IL-22 production." (PMID 40806121, 2025). "Here, we found that ITE, an AHR agonist that suppressed immunity in EAE and experimental colitis, activated anti-tumor immunity when combined with PD1 antibodies, suggesting that the efforts for targeting AHR shall go beyond searching for antagonists." (PMID 40283908, 2025). "Activated IDO-kynurenine-AhR axis in IBD mucosa promotes immune tolerance; IDO1 induction or AhR agonists show benefit in DSS-induced colitis." (PMID 41476956, 2025). "Our analysis found that microbiota population from anti-CD40+I3C treated mice significantly increased the expression of AhR and BD1 compared to cells cocultured with bacterial population from colitis mice." (PMID 39894796, 2025).
colitis (continued). "Similar to in vivo colitis models, our analysis found that DSS+I3C treatment significantly increased the mRNA and protein expression of AhR and BD‐1 in CECs MC38 and Caco2 when compared to DSS alone, especially at higher doses of I3C." (PMID 40410944, 2025). "High indole-3-lactic acid (ILA) production is a key tryptophan metabolic characteristic of L. plantarum which activated AHR downstream signaling (such as CYP1A1, IL-22, and STAT3) to alleviate colitis." (PMID 41019044, 2025). "We cocultured a bacterial population from the ileal contents of normal, anti-CD40-induced colitis, and anti-CD40+I3C treated mice with CECs MC38 for 24 hours and examined AhR and BD1 mRNA and protein expression." (PMID 39894796, 2025). "A novel anti-colitis mechanism of oligofructose (FOS) promotes the production of indole-3-acetic acid (IAA) and indole propionic acid (IPA) to trigger AhR/IL-22 axis activation by alleviating intestinal dysbiosis and modulating microbial tryptophan metabolism." (PMID 41019044, 2025). "For instance, 6-formylindolo [3,2-b]carbazole (FICZ) activates AHR to inhibit DSS-induced intestinal damage and inflammatory cell infiltration, thereby alleviating colitis in mice." (PMID 41155173, 2025). "L. paracaseiL21 and its heat-inactivated postbiotic mitigated DSS colitis similarly attenuated DSS-colitis by modulating the NF-κB and HIF1α/AhR-IL-22-MUC2 axes." (PMID 40806121, 2025). "Due to the fact that Paneth cells in the intestinal Lieberkühn’s crypt produce mouse α-defensins, we analyzed the expression of AhR and α-defensin 1 in IECs from control and mice with TNBS-, Anti-CD40-, and DSS-induced colitis." (PMID 39894796, 2025). "In particular, AhR activation by I3C or TCDD, well-characterized ligands for AhR, induced the mRNA and protein expression of α-defensin 1 in IECs from multiple colitis mouse models and various epithelial cells in vitro." (PMID 39894796, 2025). "BTW regulated Trp metabolism to increase metabolite levels, activate the AHR/IL-22 pathway to restore intestinal barrier function, and significantly alleviated DSS-induced colitis." (PMID 38974042, 2024). "It is revealed that colitis occurrence is influenced by CARD9, which alters the tryptophan in the gut microbiota, making it an aryl hydrocarbon receptor (AhR) ligand." (PMID 39408347, 2024). "Administration of the AhR agonists induces IL-10 production and suppresses DSS- or trinitrobenzene sulfonic acid (TNBS)-induced colitis in humanized mice." (PMID 39767818, 2024). "Reduced Odc1 expression was confirmed by real-time PCR and western blot analysis in WT and AhR-/- BMDMs, as well as in colon tissues in the context of DSS-induced colitis." (PMID 39113799, 2024). "In contrast, treatment of mice with an AhR antagonist reduced IL-22 production and increased the severity of inflammation in a TNBS-induced mouse colitis model." (PMID 39113799, 2024). "Collectively, these data suggest that macrophage-specific AhR activation is required to confer protection from DSS-induced colonic damage and colitis." (PMID 39113799, 2024). "Bacteroides thetaiotaomicron effectively alleviates colitis by increasing levels of IAA and its ligand AhR." (PMID 39640549, 2024). "In contrast, treatment with an AhR antagonist reduced IL-22 levels and exacerbated inflammation in a murine model of TNBS-induced colitis." (PMID 39767818, 2024). "AHR and CYP1A1 were significantly downregulated in DSS-induced colitis mice, whereas they were significantly upregulated by BTW treatment." (PMID 38974042, 2024). "In fact, they suggest that Lactobacillus reuteri induced LPLs to secrete IL-22 through AhR and then activated STAT3 phosphorylation to counteract epithelial damage in DSS-induced colitis mice." (PMID 39517263, 2024). "Previous studies revealed global AhR knockout in mouse models of colitis led to increased colitis disease severity, and IBD patients were shown to have decreased activation and expression of AhR." (PMID 38397081, 2024).
colitis (continued). "Briefly, SH‐enriched A. onderdonkii promoted the production of its microbial metabolite 5HIAA, which acts as a potent ligand to activate AhR signaling, thereby significantly ameliorating DSS‐induced colitis in mice." (PMID 38882491, 2024). "Many of these reports attribute I3C-mediated protective effects to the ability of this compound to activate AhR, which was illustrated in one of the earliest studies showing I3C’s protective effects against DSS-induced colitis were negated in AhR-null mice." (PMID 39229279, 2024). "Specifically, we found that deletion of AhR in only IECs exacerbates inflammation, and when dietary ligands are removed, it becomes fatal in mice with chronic DSS-induced colitis." (PMID 38068838, 2023). "Other species including Propionibacterium freudenreichii ET-3, which is isolated from Swiss-type cheese, are also able to activate the AHR signaling, induced anti-microbial peptides, and improve DSS-induced colitis." (PMID 37942478, 2023). "Conversely, AHR antagonists elevated Th1 cytokines production and exacerbated the severity of TNBS-induced colitis in mice." (PMID 37942478, 2023). "Our findings reveal the importance of canonical AHR signaling, and specifically AHR-AHRE binding in protecting against intestinal inflammation and DSS-induced colitis." (PMID 36519841, 2023). "Baicalein and DIM regulates Th17/Treg differentiation via AHR activation, thereby protecting against DSS-induced colitis in mice." (PMID 37179416, 2023). "To test this, we determined the sensitivity of Ahrdbd/dbd mice, a genetically modified mouse line that express an AHR protein incapable of binding to AHREs, to dextran sulfate sodium (DSS)-induced colitis." (PMID 36519841, 2023). "In summary, our findings show that AHR-AHRE interactions are required to reduce inflammation, maintain a healthy intestinal environment, and protect against DSS-induced colitis." (PMID 36519841, 2023). "Moreover, adding Indigo Naturalis to DSS-induced colitis mice can promote the expression of IL-10 and IL-22 in colonic lamina propria lymphocytes but not in AHR-deficient mice, which may be related to reduced production of regulatory cytokines." (PMID 37179416, 2023). "In experimental colitis, the AHR agonist beta-naphthalene flavone attenuates the symptom of colitis and reduces the response of human epithelial colon cells induced by LPS treatment, suggesting that AHR activation in epithelial cells may be an important mechanism regulating intestinal inflammation." (PMID 37936710, 2023). "When glucosinolate-rich cabbage was consumed, the AHR target gene CYP1A1 was substantially upregulated in the colon, which also reduced colitis." (PMID 37179416, 2023). "Before and after the colitis generation, mice were fed with butyrate and/or VD3 by oral gavage in the absence or presence of intraperitoneal injection of AhR inhibitor for 4 and 7 days, respectively." (PMID 36678175, 2023). "Oral administration of the β-naphthoflavone (an AhR agonist) decreased the severity of colitis and the production of pro-inflammatory cytokines, such as TNF-α, IL-6, and IL-1β in DSS-induced colitis." (PMID 36672703, 2023). "It implies that AhR is involved in the united effects of butyrate and VD3 on the intestinal defense to Salmonella infection in colitis mice." (PMID 36678175, 2023). "After AhR activation after exposure to Ficz, CD4+CD8αα+ IELs resisted apoptosis and upregulate IL-15 and IL-10 in a colitis model." (PMID 35892593, 2022). "To explore the pathway by which L-fucose acts on CD4+ T cells and LPMCs, we found that the mRNA levels of AHR and its target gene, CYP1A1, were significantly elevated in the colons of colitis mice by L-fucose treatment." (PMID 36432480, 2022). "In the absence of AHR, disruption of the intestinal barrier was increased in the colitis model, whereas FICZ activated AHR to alleviate DSS-induced colitis via the MK2/p-MK2/TTP pathway." (PMID 35923391, 2022).